APP (amyloid beta precursor protein)
Diseases named in the same sentence as APP in open-access papers (continued):
Sharing a sentence is not in itself a finding about the gene and the disease.
Alzheimer disease (continued). "Understanding the physiological role of Hirano bodies and their interactions with tau and fragments of APP may provide fundamental new insights to understanding Alzheimer’s disease and the presence of Hirano bodies in other neurodegenerative diseases." (PMID 23028730, 2012). "Alzheimer’s disease (AD), the most prevalent neurodegenerative disorder, stems from a dual digestion of the amyloid precursor protein (APP) by two proteases, β and γ secretases, which release the Aβ family of aggregation-prone peptides (collectively referred to as “Aβ”)." (PMID 23908845, 2012). "Pro-inflammatory stimuli, including cytokines like Interleukin-1β, Interleukin-6 and Interferon-γ, in the brain have been proposed to exacerbate existing Alzheimer’s disease (AD) neuropathology by increasing amyloidogenic processing of APP and promoting further Aβ accumulation in AD." (PMID 22838967, 2012). "One of the problems with the classic animal models of Alzheimer’s disease (e.g. APP mutations) is that they do not reflect all of the changes see in Alzheimer’s patients, such as loss of cholinergic function or the production of tau pathology." (PMID 22654716, 2011). "Amyloid-β-precursor protein (APP) plays an important role in Alzheimer's Disease (AD) pathogenesis." (PMID 21445342, 2011). "The role of estrogens in Alzheimer's disease (AD) involving β-amyloid (Aβ) generation and plaque formation was mostly tested in ovariectomized mice with or without APP mutations." (PMID 21969914, 2011). "Thus, to understand better the molecular fundamentals of the pathogenesis of Alzheimer’s disease, it is necessary not only to determine the spatial structure of Aβ peptides and their aggregates, but also of the APP protein and its TM domain." (PMID 22649674, 2011). "Therefore, understanding for both roles of X11s in APP metabolism and transport should shed light on the molecular mechanism of Aβ generation in Alzheimer's disease." (PMID 21818298, 2011). "In addition to being a key molecule in Alzheimer's disease, Amyloid Precursor Protein (APP) and its metabolites play important roles during brain development." (PMID 21298006, 2011). "A good example of a dose-sensitive gene that does not encode an enzyme is APP, encoding amyloid precursor protein, the precursor of the toxic peptide Aβ, which accumulates in the brains of patients with Alzheimer's disease (AD)." (PMID 22013986, 2011). "Importantly, the finding of post-traumatic Aβ accumulation in 3xTg-AD mice was recapitulated in a different transgenic mouse model of Alzheimer's disease, APP/PS1." (PMID 21980472, 2011). "In the central nervous system (CNS), APP can be cleaved to generate the amyloid-β peptide (Aβ), which forms oligomers and amyloid plaques that accumulate in the limbic and cerebral cortices of Alzheimer's disease (AD) patients." (PMID 21829538, 2011). "This suggests that regulation of lysosomal traffic could regulate APP processing and that the lysosome could play a central role in the pathophysiology of Alzheimer's disease." (PMID 20409323, 2010). "It is well known that APP generates beta amyloid and plays a key role in Alzheimers disease." (PMID 20350325, 2010). "Human β-amyloid precursor protein (APP) has been the subject of intense study since it was determined that it is the precursor of the β-amyloid, the main component of neuritic plaques found in patients with Alzheimer's disease (AD)." (PMID 20809979, 2010). "In Alzheimer's disease studies, most attention has focused on the role of presenilins as key components of the γ-secretase complex, which is responsible for cleaving Aβ peptides from the APP precursor." (PMID 20927324, 2010). "Proteins expressed by HSV-1 are homologous to all of the protein products of the major susceptibility gene in Alzheimer's disease (APOE, clusterin, complement receptor 1, and PICALM) as well as to APP and tau and over 100 others implicated in genetic association studies." (PMID 21234306, 2010).
Alzheimer disease (continued). "FE65 is an adaptor protein that may influence the pathogenesis of Alzheimer Disease via its strong interaction with the intracellular tail of the beta-amyloid precursor protein (APP)." (PMID 20436672, 2010). "Indeed, increased monocytic cell surface APP is associated with HIV-associated cognitive impairment) and Alzheimer's disease and cytokine and endotoxin stimulation." (PMID 20302643, 2010). "However amyloid antibodies extracted from the serum of old APP transgenic mice potentiate the toxicity of beta-amyloid, and Alzheimer's disease patients display an enhanced immune response to the peptide." (PMID 21234306, 2010). "KIF5 has been suggested to bind directly to amyloid precursor protein (APP), a transmembrane protein of which proteolytic fragments give rise to amyloid plaques in Alzheimer's disease patients, although some other studies were unable to find evidence for a direct interaction." (PMID 19653898, 2009). "Increasing the α-secretase cleavage of APP represents a plausible strategy for the treatment of Alzheimer disease, because via this route it is possible to decrease the concentration of neurotoxic Aβ peptides and to increase the amount of neuroprotective APPsα simultaneously." (PMID 19196476, 2009). "If APP does indeed function as a dependence receptor, Alzheimer's disease may be considered a "state of altered dependence"." (PMID 19558683, 2009). "Stress, and the associated increase in corticosteroids, appear to accelerate brain ageing and may increase vulnerability to Alzheimer's disease via altered APP processing." (PMID 18178006, 2008). "However if membrane-bound APP is cleaved by the β- and γ-secretase protease enzymes it generates the Aβ peptide that aggregates to form the neuritic plaques which define Alzheimer's disease pathology." (PMID 18178006, 2008). "The Amyloid precursor protein (APP) plays a central role in Alzheimer's disease (AD) pathology." (PMID 18648492, 2008). "In order to learn whether this interaction might have important physiological consequences, particularly in Alzheimer disease (a condition with disordered APP metabolism), several Arrowsmith searches were performed." (PMID 16817965, 2006). "Alzheimer's disease (AD) is characterized pathologically by extracellular fibrillar deposits in the parenchyma of the brain which are composed of the β-amyloid (Aβ) peptide 1–40 and 1–42 fragments of the amyloid precursor protein (APP)." (PMID 17005052, 2006). "The amyloid precursor protein (APP) is a single-pass transmembrane protein that gives rise to the small peptides (known as Aβ) that form amyloid deposits in the brains of patients with Alzheimer's disease (AD)." (PMID 16095541, 2005). "A vast majority (>95%) of late-onset Alzheimer’s disease(LOAD) patients develop cognitive dementia that was not due to mutationsin familial genes (amyloid precursor protein (APP) or presenilin-1or −2 (PS1 or PS2)), hinting at factors other than geneticsexacerbating or promoting the disease." (PMID 41481312, 2026). "In addition, we have shown that gene expression profiles from our mouse models of AxD are highly congruent with a transcriptomic portrait of human Alzheimer's disease, second only to the Alzheimer's APP/PSEN1 mouse in comparison with large-scale gene expression data from over 500 animal models." (PMID 40064497, 2025). "For example, human Chr21 carries APP that underlies amyloid plaques in Alzheimer’s disease; yet a 50% increase in APP abundance may not fully explain early-onset disease in people with DS." (PMID 41248159, 2025). "One type of ADRD, early-onset Alzheimer’s disease (EOAD), afflicts about 5% of the population diagnosed with ADRD, while mostly heritable, the known genes associated with this prognosis are amyloid precursor protein (APP), presenilin 1 (PSEN1), and presenilin 2 (PSEN2)." (PMID 38967905, 2025).
Alzheimer disease (continued). "Most APP-related studies in DS have focused on adult neurological effects rather than developmental effects of APP dosage imbalance, because elevated APP expression contributes to Alzheimer's disease neuropathology and accumulation of Aβ deposits in individuals with DS." (PMID 41342252, 2025). "Lifelong choline supplementation in another Alzheimer’s disease mouse model (APP/PS1 transgenic mice), significantly diminished amyloid-β plaque load and decreased activated microglia, thereby mitigating the detrimental effects of brain inflammation associated with Alzheimer’s disease." (PMID 40821837, 2025). "We asked whether activation of the hypoxia-inducible factor (HIF) pathway via genetic deficiency of HIF prolyl 4-hydoxylase-2 (HIF-P4H-2; also known as PHD2/EGLN1) could be an Alzheimer’s disease–modifying therapy using transgenic amyloid precursor protein (APP)/presenilin 1 (PS1) female mice." (PMID 40609789, 2025). "Additionally, a case study of APP, a key protein in Alzheimer’s disease, is used as an example." (PMID 41441335, 2025). "In addition to APP, the pathogenesis of Alzheimer’s disease (AD) is significantly related to tau, and more evidence indicates that reducing tau may reduce this pathology." (PMID 40309514, 2025). "Consequently, APP has been extensively studied in the context of Alzheimer's disease (AD)." (PMID 40739894, 2025). "Amyloid beta precursor protein (APP) encodes a transmembrane protein with essential roles in many neurodevelopmental processes, such as neurogenesis, neurite outgrowth, axonal guidance, and synaptogenesis, and is central to the pathogenesis of Alzheimer’s disease (AD)." (PMID 41561974, 2025). "Alzheimer’s disease (AD) is the most common form of dementia, characterized by the accumulation of amyloid-β (Aβ), a normal cellular product resulting from the metabolism of amyloid precursor protein (APP) and neurofibrillary tangles composed of hyperphosphorylated tau." (PMID 41277898, 2025). "Since estrogen deficiency leads to mitochondrial defects that provoke Alzheimer’s disease-associated pathological changes in a postmenopausal mouse model, the neuroprotective abilities of biochanin A were studied in an AD in vivo model with ovariectomized (OVX) APP/PS1 mice." (PMID 40429904, 2025). "While most of the Alzheimer’s disease (AD) cases are sporadic and manifest after age 65 (late-onset AD, LOAD), a subset of patients develop symptoms earlier in life (early-onset, EOAD) due to mutations in the PSEN1, PSEN2, or APP genes with an autosomal-dominant inheritance pattern (AD-EOAD)." (PMID 40869250, 2025). "Moreover, MAPK signaling is an active part of various mechanisms occurring in Alzheimer’s Disease, including neuronal apoptosis, oxidative stress, β- and γ-secretase activation at multiple levels, and stabilization of amyloid precursor protein (APP) via phosphorylation." (PMID 37284987, 2024). "While Notch proteolysis exerts crucial functions in cell differentiation and development, APP cleavage by γ-secretase results in the secretion of amyloid β-protein (Aβ), which accumulates in the brains as senile plaques (SP), one of the pathological hallmarks of Alzheimer disease (AD)." (PMID 38791456, 2024). "On the other hand, a study in the APP/PS1 mouse model of Alzheimer's disease demonstrated that overexpression of ADAM17 could influence cerebrovascular functions and cognitive abilities, highlighting its potential role in AD pathology and as a therapeutic target." (PMID 38963109, 2024).
Alzheimer disease (continued). "AD is characterized by amyloid deposits whose major protein component is beta A4; beta A4 is a product of APP that is associated with a decrease in established Alzheimer’s disease; however, sAPPα and -β and their variants were not available on the SomaScan panel to measure." (PMID 38256230, 2024). "Thus, a better understanding of APP’s biology may improve our understanding of the molecular processes involved in Alzheimer’s disease." (PMID 38992438, 2024). "In addition to the gene dosage and the effect of an additional APP copy on chromosome 21, other genes on the same chromosome could also play a role in the development of Alzheimer’s disease in patients with Down syndrome." (PMID 39518906, 2024). "While the target gene APP is identified as a target of Florbetapir F-18, this drug’s primary use currently lies in diagnostic imaging, specifically as a radiopharmaceutical compound in PET scans to visualize amyloid plaques, a key indicator of Alzheimer’s Disease." (PMID 38651367, 2024). "Furthermore, recent studies suggest that the deposition of amyloid beta (Aβ) peptides, proteolytic fragments of APP, could be the overlapping molecular mechanism between Alzheimer’s disease and CAD." (PMID 39119577, 2024). "Alzheimer’s disease (AD) is a multifactorial disease characterized by numerous pathologies including increased neuroinflammation, decreased synaptic plasticity, dysregulated amyloid precursor protein (APP) processing, and aberrant tau protein post-translational modifications." (PMID 37171575, 2023). "Therefore, APP processing control by sodium-glucose cotransporter 2 inhibitors may play a pivotal role in disease-modifying therapy for Alzheimer’s disease but also diabetes mellitus." (PMID 36869919, 2023). "They reached a consensus that “senile plaque” in the brain is a special marker of Alzheimer’s disease, and this “senile plaque” is formed due to the accumulation of β-amyloid protein (a downstream product), which is produced by sequential proteolytic cleavage of APP." (PMID 36610814, 2023). "In order to obtain further insight about possible mechanisms that might explain variations in MCT4 expression between young and senescent animals, we performed RT-PCR in the frontal cortex and hippocampus of wildtype mice and subsequently in the APP/PS1 mouse model of Alzheimer’s disease." (PMID 37895298, 2023). "Altered amyloid precursor protein (APP) processing and amyloid β (Aβ) production have long been implicated in the cognitive decline associated with age-related neurological disorders such as Alzheimer’s disease (AD) and HIV-associated neurocognitive disorders (HAND)." (PMID 36576708, 2023). "However, the sporadic forms of Alzheimer’s disease accounting for 95% of the patients do not involve mutations in the APP genes." (PMID 36898995, 2023). "Our lab explored the role of H2S in memory and cognition and we evaluated the involvement of the 3MST/H2S pathway in Alzheimer disease (AD) pathology using a symptomatic transgenic AD mouse model (APP/PS1)." (PMID 36978851, 2023). "Cleavage of APP within the extracellular region by the β-secretase protease and in the transmembrane domain by the ɣ-secretase complex results in the production of approximately 40 amino acid peptides, which aggregate into the extracellular plaques required for the diagnosis of Alzheimer’s disease." (PMID 37923712, 2023). "Interestingly, the two foremost biological networks of these targets center on two proteins associated with neurodegeneration: the amyloid precursor protein (APP), which is linked to Alzheimer’s disease, and Huntingtin (HTT), a genetic mutation associated with Huntington’s disease." (PMID 37569576, 2023). "On APP, ADAM10 activity causes the generation of a C-terminal membrane-anchored fragment and a neuroprotective soluble ectodomain (sAPPα), precluding amyloid-β (Aβ) formation and their aggregation leading to amyloid plaque load that is a hallmark of Alzheimer’s disease (AD)." (PMID 36674432, 2023).
Alzheimer disease (continued). "In addition, upregulation of amyloid precursor protein (APP), a protein whose aberrant processing or metabolism having been implicated in Alzheimer’s disease (AD), was observed at early stages of ALS and FTD, presumably as a compensatory response to neuronal damage or impairment of axonal transport." (PMID 36764521, 2023). "In support of this approach, hCOs with APP and PSEN1 mutations, hCOs generated from Down syndrome iPSCs, and hCOs carrying the Alzheimer disease (AD) APOE4 risk allele show AD hallmarks, including amyloid-beta accumulation and tau hyperphosphorylation." (PMID 35985329, 2022). "Regarding Alzheimer’s disease (AD), microdialysis assays showed that orexin treatment resulted in the regulation of amyloid beta peptide (Aß) levels in the hippocampal interstitial fluid of a transgenic model that overexpresses a mutant form of the amyloid precursor protein (APP)." (PMID 36361598, 2022). "Thus, we hypothesized that AAV-mediated overexpression of Gas6 in the hippocampus would alleviate plaque pathology, reduce neuroinflammation, and improve behavior in the APP/PS1 murine model of Alzheimer’s disease." (PMID 35130912, 2022). "Therefore, we hypothesized that AAV-mediated overexpression of Gas6 would alleviate plaque pathology, reduce neuroinflammation, and improve behavior in the APP/PS1 model of Alzheimer’s disease." (PMID 35130912, 2022). "Furthermore, as changes in lysosome size was described in APP mouse transgenic model of Alzheimer’s disease, we asked whether detectable changes in lysosome diameter can be quantified on 24- or 48-h exposure to 1 μm AβF and AβO." (PMID 35470226, 2022). "Intriguingly, KD was shown to reduce amyloid-β42 and β40 in APP (Amyloid Precursor Protein) mice, a mouse model for Alzheimer’s disease, and recently it has been suggested that nutritional ketosis could improve several astrocytic functions, while reducing astrogliosis." (PMID 36407529, 2022). "Additionally, the main targets APP and GSK3β in the Alzheimer’s disease pathway were verified." (PMID 35462916, 2022). "Amyloid plaques caused by an amyloid precursor protein (APP) gene mutation, neurofibrillary tangles (NFT) caused by tau protein gene mutation, missense mutations of the presenilin-1 (PS-1) gene, and the apolipoprotein E typeE4 (ApoE4) allele are closely associated with Alzheimer’s disease." (PMID 35624994, 2022). "al. have declared the phosphorylation of amyloid precursor protein (APP) is one of the keys for modulating the generation of amyloid-β and phosphorylation abnormalities of APP would lead to abnormal accumulation of amyloid-β in the central nervous system, which is a hallmark of Alzheimer’s disease." (PMID 35163663, 2022). "Therefore, our aim was to establish 89Zr radiochemistry for brain application by performing ex vivo and in vivo biodistribution studies of a bispecific anti-amyloid-beta aducanumab derivate mAbAdu-scFab8D3 (Adu-8D3), in an APP/PS1 mouse model of Alzheimer's Disease." (PMID 36276653, 2022). "Remarkably, this study showed that a lentivirus-driven HDAC1::SUMO translational fusion protein could rescue the learning and memory deficits of an APP/Presenilin 1 murine model of Alzheimer's disease, suggesting that HDAC1 SUMOylation may be neuroprotective in response to Aβ accumulation." (PMID 34003109, 2021). "Additionally, transgenic mice expressing the same APP mutation showed memory impairment and pathological findings similar to patients with Alzheimer’s disease despite the absence of amyloid plaques." (PMID 34443678, 2021). "In addition, studies of NRBF2 in Alzheimer’s disease revealed that NRBF2 plays an important role in regulating the degradation of APP C-terminal fragments by modulating autophagy and could be a potential therapeutic target for Alzheimer’s disease." (PMID 34530854, 2021).